IL4 (interleukin 4)
Diseases named in the same sentence as IL4 in open-access papers (continued):
Sharing a sentence is not in itself a finding about the gene and the disease.
tumor (continued). "This design enables the virus to replicate exclusively within hypoxic, HIF-active tumor cells, leading to immunogenic cell death and local IL-4 production that both stimulate anti-tumor immunity and exert anti-angiogenic effects." (PMID 41313526, 2025). "cultured TILs express IFN-γ, IL-4, IL-5, TNFα, IL-8, IL-10- and, to a lesser extent, IL-2 mRNAs while, in the corresponding tumor samples only TNF-α, IL-8 and IL-10- transcripts were expressed." (PMID 40092980, 2025). "In contrast to the previous experiment started at 8 weeks of age to study tumor progression, the alterations in myeloid and T cell populations were accompanied by a significant decrease in IL-6 and IL-4 serum levels in OGP-treated mice." (PMID 40307509, 2025). "ILC2s, dependent on the GATA-binding protein 3 (GATA3) transcription factor for development, exert anti-tumor activity by secreting type 2 cytokines such as IL-4 and IL-13 in the tumor microenvironment, influencing tumor prognosis." (PMID 40661781, 2025). "In particular, GM-CSF, IL-4 and IL-5, which are produced by tumor-infiltrating ILC2s, are crucial for the recruitment and cytotoxicity of eosinophils in tumor models." (PMID 39962262, 2025). "IL-4 and IL-13 drive a unique “Mac-e” state that is characterized by immunosuppressive genes and reparative M2-like states and related to enhancing tumor cell proliferation and suppressing CD8+ T cell activation." (PMID 41467185, 2025). "Future research can further explore the artificial engineering of IL-4, IL-10, and other cytokines to remodel their immune regulatory functions, thus expanding their application prospects in tumor immunotherapy." (PMID 41226585, 2025). "IL-4 also upregulates PD-L1 in tumor cells, which impairs antigen presentation and promotes the escape of the immune system." (PMID 41376630, 2025). "This novel NKG2D-CAR-T cell approach effectively overcomes IL-4-mediated immunosuppression in solid tumors, demonstrating superior tumor eradication compared to conventional NKG2D-CAR-T cells." (PMID 40612946, 2025). "We found that DSV, similarly, correlated positively with faster tumor growth, higher serum IL-4 and reduced Eotaxin and IL-17 levels." (PMID 39744230, 2025). "In the tumor site, release of cytokines, including IL-13 and IL-4, induces polarization toward M2-type macrophages." (PMID 40969416, 2025). "Mice vaccinated with FL/GM-DCs exhibited a substantial reduction in tumor growth relative to the control group and GM/IL4-DC-vaccinated mice." (PMID 40977690, 2025). "In response to tumor-derived interleukin-4 (IL-4), osteopontin promotes the polarization of macrophages toward a pro-tumorigenic phenotype, characterized by elevated expression of IL-4 receptors and arginase-1." (PMID 41404065, 2025). "Tumor-derived cytokines (IL-4, IL-10, TGF-β) activate STAT6 and SMAD pathways, reinforcing M2 immunosuppression." (PMID 40417220, 2025). "IL-4-driven Th2 polarization reshapes the TME, reducing cytotoxic T cell infiltration, increasing regulatory T cells and tumor-associated macrophages, and impairing immune surveillance." (PMID 40864740, 2025). "Depending on the signals in the microenvironment, TAMs in the Br-TME polarize into two distinct phenotypes: an antitumor subtype (lipopolysaccharide-induced macrophages, M1 TAMs) and a tumor-promoting subtype (IL-4-stimulated macrophages, M2 TAMs)." (PMID 40649751, 2025). "In our in vitro model, TTFields converted IL-4-polarized macrophages (a proxy for tumor TAMs) to express key co-stimulatory and antigen-presenting molecules and to secrete pro-inflammatory mediators." (PMID 41465516, 2025). "In contrast, M2 macrophages, driven by IL-4, IL-10, and TGF-β, are associated with tumor progression via immunosuppression, angiogenesis, and tissue remodeling." (PMID 40330466, 2025).
tumor (continued). "TAM polarization toward the M2 phenotype, driven by IL-4 or IL-13, dampens anti-tumor T cell responses and enhances tumor-promoting processes including angiogenesis, proliferation, and invasion." (PMID 41058699, 2025). "In particular, hypoxic and necrotic regions of GBM secrete chemokines such as interleukin-4 (IL-4) and interleukin-10 (IL-10), driving a shift from M1 (anti-tumor) to M2 (pro-tumor) TAMs." (PMID 40585979, 2025). "Historically, Th2-polarized responses were thought to dampen Th1-mediated cytotoxicity and favor tumor growth by skewing immunity toward interleukin (IL)-4/IL-13-driven humoral pathways." (PMID 40428397, 2025). "Depletion of FAP+ CAFs in mammary tumor models has shown a shift from IL-4 and IL-6 expression to IL-2 and IL-7 expression in tumor homogenates." (PMID 40236693, 2025). "Conversely, de novo serine synthesis was increased at 24 h following IL4 treatment or tumor CM stimulation, and genetic ablation of Phgdh significantly downregulated the expression of M2 markers." (PMID 38409249, 2024). "Cytokines secreted by T cells were assayed, including TNF-α, IL-10, and IL-4, associated with generating antitumor CTL responses and tumor immune surveillance." (PMID 39772073, 2024). "IL-4 and IL-13, as well as IL-10, have been demonstrated to play important roles during primary tumor progression in mouse models of cancer." (PMID 39599846, 2024). "These signals can promote either a pro-tumor M2 phenotype (e.g., IL-4, IL-10, TGF-beta, and CCL2) or can drive TAMs towards an anti-tumor M1 phenotype (e.g., IFN-gamma and TNF-alpha)." (PMID 38730679, 2024). "In the orthotopic mouse model, p-FAK, p-STAT3 and IL-4 were significantly decreased in tumor tissues of Postn-/-Rag1-/- mice compared to Postn+/+Rag1-/- mice." (PMID 38773979, 2024). "TAMs can be polarized into either M1 phenotype (with anti-tumor activity) or M2 phenotype, driven by hypoxia and IL-4 (with pro-tumor activity)." (PMID 39765634, 2024). "Numerous studies have highlighted that IL-13 and IL-4 have a synergistic effect, and their expression promotes tumor cell growth and proliferation in CTCLs." (PMID 38607023, 2024). "This treatment triggered a Th1 cytokine shift characterized by increased IFN-γ and TNF-α levels and decreased IL-4 levels, suggesting a robust anti-tumor response." (PMID 39294673, 2024). "Inversely, a lower proportion of Th2 (IL-4+ CD4+ T cells) cells was detected in both tumor types compared to NS (BCCs, median: 8.3%, range: 2.4–15.6; SCCs, median: 7.3%, range: 3.7–13.1; NS, median: 19.2%, range: 9.4–30.9)." (PMID 38891095, 2024). "The most well-known pathway for Arg1 induction is through IL-4-STAzzT6, an anti-inflammatory and tumor-supportive signaling pathway." (PMID 38422022, 2024). "Tumor-promoting factors, including IL-4, EGF, and TGF-β, induced HES1 expression, but Rbpj knockdown attenuated these responses in both murine and human macrophage cell lines." (PMID 39702544, 2024). "Conversely, M2 macrophages, activated by IL-4 and IL-10, contribute to tumor progression and metastasis." (PMID 38293522, 2024). "IL-4, IL-5, and IL-13, which are related to the Th2 immune response, can create an immunosuppressive environment that favors tumor growth." (PMID 39456897, 2024). "The other activated macrophage phenotype, M2-like TAMs, are switched on by Th2 cells cytokines such as IL-13, IL-10 and IL-4, leading to tumor progression, inducing angiogenesis and metastasis, and inhibiting the anti-tumor response." (PMID 39050852, 2024). "This is in addition to the better studied role of IL4 signaling in immune cells, driving immunosuppression and tumor progression indirectly." (PMID 38731867, 2024). "Tumor cells predominantly express Th2 type cytokines, such as IL-4, IL-6, and IL-10 which aid tumor cells in evading immune destruction by inhibiting the differentiation of CD8+ T cells." (PMID 38255791, 2024).
tumor (continued). "For instance, CD4+ Th-2 cells, innate lymphoid cells (ILCs)-2- and T-reg lymphocytes that produce IL-4, IL-13 and IL-10 can sustain the formation of M2-like macrophages with a pro-tumor phenotype." (PMID 38426089, 2024). "As observed in the tumor context, PD-1 blockade induced the production of IL-4 in the draining lymph node." (PMID 38417020, 2024). "We observed that interferon-alpha (IFN-α) and interferon-gamma (IFN-γ) very strongly induced the activation of the STAT1 protein, whereas IL-6 and IFN-α activated STAT3 and IL-4 activated STAT6 in all examined tumor cell lines." (PMID 38396958, 2024). "Twice weekly intravenous injections of tumor-bearing mice with 0.1 mg 4T-Trap selectively inhibited Th cell TGF-β signaling in tumor-draining lymph nodes, leading to an IL-4-dependent tumor vasculature reorganization and cancer cell death in four weeks." (PMID 38675493, 2024). "Of note, anti-IL-4 mAb also reduced the activity of anti-PD-1 on tumor growth as observed with FTY720 or FX-1 treatment, a finding compatible with a partial role of peripheral T cells during anti-PD-1 therapy." (PMID 38417020, 2024). "Tumor cells not only can upregulate the level of GM-CSF and IL-4, but they also express PD-L2 on their surface for immune suppression." (PMID 38255322, 2024). "On the other hand, AgNPs-G treatment significantly decreased the levels of IL-2, IL-4, and IL-10 in tumor tissue compared to the control group." (PMID 39126001, 2024). "The OC has a tumour microenvironment that is immunosuppressive and has high levels of cytokines like IL-4 and IL-13 that promote the recruitment of immunosuppressive cells." (PMID 38974022, 2024). "Produced by multiple components in the TME, IL-4 and IL-13 and their receptor systems are able to influence malignant behavior, via altering tumor proliferation, survival, and metastatic ability or suppressing tumor-directed immune surveillance mechanisms." (PMID 38726003, 2024). "IL-4, a cytokine secreted by T cells, B cells, and macrophages, potentially facilitates tumor progression within this microenvironment." (PMID 39207449, 2024). "IL-4-driven activation of STAT6 inhibited TRIM24 activity, promoting the polarization of macrophages toward the tumor-associated phenotype in a murine model of melanoma." (PMID 39516356, 2024). "IL4 is a gene that codes for a key T helper 2 (Th2) cytokine that promotes tumor growth by increasing proliferation and survival." (PMID 38032489, 2024). "The results demonstrated that lymphocytes cultured with oncogenes-transfected tumor cells promoted an increase in the release of the cytokines IL-2, IL-4, IL-10, and TNF-α, with differences in the releases from different transfected oncoproteins." (PMID 39599846, 2024). "OPN promotes tumor cell proliferation in vitro and in vivo, recruits macrophages in a recurrent TME, and synergizes with tumor-derived IL-4 for them to acquire pro-tumorigenic characteristics." (PMID 39448577, 2024). "While tumor immunity is mainly governed by Th1-mediated cellular responses, we observed that preexisting higher levels of IL-5, IL-4, and IL-10 were also correlated with better clinical responses." (PMID 38231411, 2024). "Cytokines secreted by Th2 cells, such as IL-4 and IL-13, disrupt the balance between Th1 and Th2, shifting the immune response from Th1 to Th2, thereby promoting tumor growth." (PMID 39867914, 2024). "IL4 and IL4R expression was higher in Tfh tumor cells in the RR group, whereas IL‐4+/CD4+ cells and IL‐4R+/CD20+ cells showed cell communication." (PMID 38145335, 2024). "Both TGF-β and the combined profile of IL-4/IL-13 signaling pathways were found to be consistently upregulated across almost all tumor types." (PMID 39035007, 2024). "Here, we found that the T helper 2 (Th2) cytokine interleukin-4 and tumor-conditioned media upregulate the expression of PHGDH in macrophages and promote immunosuppressive M2 macrophage activation and proliferation." (PMID 38409249, 2024).
tumor (continued). "Bone marrow-derived macrophages play an important role in the tumor microenvironment by secreting various cytokines, such as IL-6 and IL-4, thereby regulating the growth, invasion and migration of tumor cells." (PMID 38261741, 2024). "Meanwhile, CD4 + T cells downregulate interferon-γ and IL-2, increase the production of IL-4 and IL-5, further promoting tumor development." (PMID 39020276, 2024). "And the results revealed a positive correlation between IL-4 level in serum and FcγRIIB expression of M2 macrophages cells in tumor tissues." (PMID 39003253, 2024). "To test the importance of IL-4 in anti-PD-1 mAb activity in the lymph node, we treated tumor-bearing mice with anti-IL4 mAb in the context of anti-PD-1 mAb treatment." (PMID 38417020, 2024). "The recruitment of eosinophils into the oral tumour site is mediated by inflammatory cytokines and chemokines, primarily attributed to IL-4 and IL-13, which are secreted from T helper cells (Th2)." (PMID 38673958, 2024). "The interaction between tumor cells and other cell types via the interleukin‐4 (IL4)/IL4 receptor (IL4R) pair was considerably enriched in cGAS+/STING+ Tfh tumor cells." (PMID 38145335, 2024). "We observed a notable increase in both protein and mRNA levels of IL-4 in tumor cells indirectly co-cultured with WT CAFs compared to those cultured alone or co-cultured with KO CAFs." (PMID 38773979, 2024). "Compared to that of the PD-1 antibody group, the tumor growth in the IL-4 recipient xenograft mice showed an obvious phenotype of resistance to anti-PD-1 therapy." (PMID 39003253, 2024). "In contrast, M2 macrophages are polarized by IL-4 and secrete anti-inflammatory cytokines, such as IL-10, promoting tumor progression." (PMID 39795180, 2024). "Both IL-9 and IL-4 are components of the tumor’s immunosuppressive microenvironment, aiding cancer cells in evading immune responses." (PMID 39727942, 2024). "Compared to DCs obtained through the traditional method (cultured in medium containing GM-CSF and IL-4), DCs cultured with PBMCs, and IL-2 exhibited increased tumor infiltration capacity, potentially facilitating sustained T cell immunity." (PMID 38554155, 2024). "This shift will increase the immunosuppressive cytokines (IL-2, IL-4, IL-7, IL-13, and IL-15) production by neoplastic elements which lead to tumor growth and spread." (PMID 38850434, 2024). "IL-4 is involved in multiple immunological functions, both pro-tumor and anti-tumor depending on the context." (PMID 38443899, 2024). "For instance, eosinophils can exhibit pro-tumour effects; IL-4 has the potential to facilitate tumour growth due to its anti-apoptotic properties whilst also having anti-angiogenic properties that inhibit tumour growth." (PMID 38673958, 2024). "Our experimental findings have shown a significant increase in IL-4 levels in the serum of tumor-bearing mice." (PMID 39452870, 2024). "Th2 reactivity or IL4 can promote anti-tumor response in some models, whereas donor T cell Th2 reactivity can have an adverse effect on anti-tumor immunity in others." (PMID 39796136, 2024). "NKT cells activate the release of IFN-γ in HCC mainly through exogenous glycolipids (a-GalCer) to exert anti-tumor effects, and IL-4 can also activate N KT cells." (PMID 38245747, 2024). "We also analyzed the expression of other Th2 cytokines besides TGFβ-1 (IL-4 and IL-6) in spleen and tumor samples, but treatment with mHAdLyp.sT didn’t lead to any significant changes when compared to the buffer group (data not shown)." (PMID 38267626, 2024). "It was also shown that IL-4 secreted by tumor cells significantly influence tumor infiltrates such as macrophages or CD8 lymphocytes." (PMID 39057050, 2024). "The immunosuppressive cytokines, TGF-β, IL-4, IL-10, and IL-35, are the cytokines that are dominant in the tumor environment in different tumors." (PMID 38850434, 2024).
tumor (continued). "Both tumor cells and M2a release IL-4, which promotes the polarization of additional macrophages towards M2a and leads to the production of more IL-4, thereby creating a positive feedback loop." (PMID 39796695, 2024). "IL-6, IL-10, and IL-4 are considered the main Th2 immune cytokines, mainly encouraging tumor growth by hindering the host’s immune system." (PMID 38361933, 2024). "CTSL, produced by both tumor cells and macrophages, promotes breast cancer metastasis by driving M0 to M2 differentiation via IL-4." (PMID 39736788, 2024). "In contrast, M2 macrophages, activated by IL-4 and IL-13, contribute significantly to tumor growth, metastasis, and immune evasion." (PMID 39766056, 2024). "Meanwhile, in order to detect the glycolysis of each group in vivo, We also found that IL-4 significantly enhanced total protein lactation in tumor interstitial tissue." (PMID 39003253, 2024). "The inflammatory milieu within the TME, augmented by the exosomal secretion of transforming growth factor beta (TGF-β), interleukin-4 (IL-4), and interleukin-10 (IL-10), modulates the local immune response to favor tumor progression." (PMID 39766226, 2024). "M2 stimulates tumor growth and invasion through the secretion of IL-4, IL-13, IL-10, vitamin D3, and glucocorticoids." (PMID 39201801, 2024). "In this study, the role and mechanism of PD-L1 in tumor immune escape were explored, with particular focus on the promotion of IL-6 and IL-4 secretion by activation of the Notch-1/IRE1/XBP1s signaling pathway in macrophages." (PMID 38261741, 2024). "Collectively, these data suggest that POSTN promotes proliferation and IL-4 production in tumor cells through the integrin-FAK-STAT3 signaling." (PMID 38773979, 2024). "We provide evidence that CD8+ T cells expanded through the Tfh/IL-4 axis contribute to anti-tumor activity." (PMID 38417020, 2024). "Immunohistochemistry was used to detect the expression of FcγRIIB in mouse xenograft tumors, and it was found that IL-4 significantly enhanced the expression of FcγRIIB in subcutaneous tumor interstitial tissue." (PMID 39003253, 2024). "CD4+IL-4+ T lymphocytes act as indirect promoters of invasion and metastasis by regulating the increase in macrophages in the tumour microenvironment." (PMID 38662248, 2024). "We conducted tumor treatment-related immune cell and Th1/Th2 subset detection in the patient, comparing the concentrations of 6 cytokines (IL-2, IL-4, IL-6, IL-10, TNF-α, and TNF-γ) and various immune cells in peripheral blood before and after treatment." (PMID 39871939, 2024). "Conversely, treating tumor-bearing mice with IL-4 complexes (IL-4 bound to anti-IL-4 mAb to enhance its in vivo half-life) recapitulated the effect of anti-PD-1 mAb on OT-I CD8+ T cell expansion and TNF-α+IFN-γ+ double-producer T cells." (PMID 38417020, 2024). "In sum, our results suggest that Tfh cell–derived IL-4 promotes antigen-specific CD8+ T cell responses in tumor-draining lymph nodes during anti-PD-1 therapy." (PMID 38417020, 2024). "Th1 subtype of CD4+T cells directly destroy tumor cells by secreting IFN-γ and TNF, whereas Th2 subtype secretes anti-inflammatory mediators such as IL4, which suppress immunity and support tumor growth." (PMID 39350256, 2024). "For instance, silencing lncRNA NR_109 in M2 macrophages significantly hindered IL-4 induced M2 macrophage polarization and depressed their capacity to support tumor cell proliferation and metastasis." (PMID 39676873, 2024). "On the other hand, studies confirmed that the level of IL-4 in cancer patients is higher, and there is a high level of IL-4R receptor expression on the surface of tumor cells." (PMID 39221149, 2024). "Accordingly, other studies found tumour MDSCs to have superior immunosuppressive functions over MDSCs found in the periphery in line with the heightened Arg1 expression, and indeed tumour MDSCs strongly express the IL-4 and IL-13 receptors." (PMID 38464388, 2024).